CA2 (carbonic anhydrase 2)
Diseases named in the same sentence as CA2 in open-access papers (continued):
Sharing a sentence is not in itself a finding about the gene and the disease.
melanoma (11 papers, 2010 to 2024). A malignant, usually aggressive tumor composed of atypical, neoplastic melanocytes. "In contrary, increased expression of several types of Ca2+ channels was identified in both melanoma cells and melanoma tissues, and the inhibition of these channels led to increased cell death and decreased metastatic activity." (PMID 28596940, 2017). "For example, CA2 reduced melanoma cell proliferation via cell cycle arrest in the G0/G1 phase, and expression of cyclins." (PMID 27537898, 2016). "In this review, we summarize the current knowledge about the expression of different Ca2+ channels in the plasma membrane of melanoma cells and its impact on oncogenic Ca2+ signaling." (PMID 25710007, 2015). "Strikingly, in this study the viability of melanoma cells was dose-dependently depressed in the presence of menthol, indicating that these channels underlie tumor progression via the Ca2+ handling pathway and suggesting TRPM8 Ca2+ channels as novel targets of drug development for malignant melanoma." (PMID 25710007, 2015). "The emergence of evidence has revealed that TRPM2, a highly Ca2+ permeable cation channel, acts as a regulator in cancer growth and survival, and is correlated with poor prognosis in patients with breast, gastric, pancreatic, prostate, head and neck cancers, melanoma, and neuroblastoma." (PMID 37569287, 2023).
glioma (10 papers, 2010 to 2024). A benign or malignant brain and spinal cord tumor that arises from glial cells (astrocytes, oligodendrocytes, ependymal cells). "To this end, we assessed the abundance of mRNA encoding Ca2+ channels in our two human glioblastoma cell lines and in glioma resection specimens by RT-PCR and by querying the TCGA low grade glioma and provisional glioblastoma data bases, respectively." (PMID 30669316, 2019). "In gliomas, CA2 expression not only seems to correlate with malignancy but also with survival, suggesting a link between high CA2 expression levels and a shorter overall survival." (PMID 31262047, 2019). "Among up-regulated genes, we identified carbonic anhydrase 2 (CA2) as a candidate gene correlated with glioma malignancy and patient survival." (PMID 31262047, 2019). "The main types of Ca2+ channels described in the literature and expressed by gliomas are voltage-dependent channels (Cav1 = Type L; Cav2 = Type P/Q, R, N; Cav3 = Type T) and purinergic receptors." (PMID 31531023, 2019). "In order to determine if glioma cells in situ have a similar Ca2+-activated K+ channel expression profile, we isolated mRNA from a surgical sample that was histopathologically identified as a GBM." (PMID 20808839, 2010). "The detection of the IK1 subtype of Ca2+-activated K+ channels in glioma cells may be of substantial importance." (PMID 20808839, 2010).
colorectal cancer (9 papers, 2005 to 2025). A primary or metastatic malignant neoplasm that affects the colon or rectum. "Furthermore, we investigated gene expression changes in IL8, GZMB and CA2, which have been reported to be associated with colorectal cancer progression, at all time-points in the 15 tumor cases." (PMID 24573535, 2014). "The down-regulation of cytosolic CA I, II and XIII in colorectal cancer may result from reduced levels of a common transcription factor or loss of closely linked CA1, CA2 and CA13 alleles on chromosome 8." (PMID 15836783, 2005). "However, CA2 inhibited the growth of cancer cells in colorectal cancer." (PMID 36359865, 2022). "We revealed that quercetin, stigmasterol, kaempferol, baicalein, and acacetin played a critical role in colorectal cancer by affecting PTGS2, NR3C2, CA2, and MMP1." (PMID 34125845, 2021). "NR3C2, CA2, and MMP1 were identified as key target proteins in another network pharmacological pharmacology analysis of the colorectal cancer." (PMID 34381520, 2021). "The present study identified six hub targets—GOT1, CYP2C9, CYP34, CYP1A2, CA2, and ABAT—that are involved in five core pathways related to HQD’s effects on malignant progression in colorectal cancer liver metastases, integrating transcriptomic and metabolomic analyses." (PMID 40732339, 2025).
hepatocellular carcinoma (8 papers, 2020 to 2024). A malignant tumor that arises from hepatocytes. "CA2 is upregulated in cancers (e.g. hepatocellular carcinoma) and plays a role in the establishment of tumor endothelium." (PMID 37379157, 2023). "The clinicopathological correlation analysis showed that CA2 was significantly downregulated in tumor metastases, such as hepatocellular carcinoma (p-value = 0.026)." (PMID 36631756, 2023). "Studies have shown that patients with a high CA2 expression have better disease-free survival and overall survival than those with a low expression in hepatocellular carcinoma." (PMID 37895185, 2023). "CA2 is a factor that inhibits metastasis and EMT and is associated with good OS in patients with hepatocellular carcinoma." (PMID 36338624, 2022).
Hypertension (8 papers, 2013 to 2023). The presence of chronic increased pressure in the systemic arterial system. "In the meanwhile, the feasibility of targeting Ca2+ channels has already been highlighted by clinical experience of voltage gated Ca2+ channel blockers for the treatment of hypertension, and also by the viable phenotype of TRPM8−/− mice." (PMID 35361751, 2022). "Emerging evidence suggests that alterations of endothelial ion channels such as SKCa channels, inward rectifier K+ channels, Ca2+-activated Cl− channels, and transient receptor potential vanilloid type 4 channels contribute to the impaired EDH during hypertension." (PMID 29361737, 2018).
pancreatic cancer (8 papers, 2016 to 2022). "Over the past years, the involvement of Ca2+ channels in PSC pathophysiology has attracted great interest in pancreatic cancer research." (PMID 34063470, 2021). "Annexin A1 (ANXA1) is a Ca2+-binding protein over-expressed in pancreatic cancer (PC)." (PMID 27412958, 2016). "As a result, ductal (CA2, CK19, and SOX9)/pancreatic cancer (EpCAM and CD44) markers decreased and acinar markers (SYP and PTF1A) increased by inhibitor treatment in KiPCs." (PMID 33233448, 2020).
colon cancer (7 papers, 2016 to 2024). "In contrast, it decreased Ca2+ ATPase PM activity in samples of normal human colon mucosa and caused no changes in colon cancer." (PMID 38338935, 2024). "The interplay of SK3, a Ca2+ sensitive K+ ion channel, with Orai1, a Ca2+ ion channel, has been reported to increase cytosolic Ca2+ levels, thereby triggering proliferation of breast and colon cancer cells, although a molecular mechanism has remained elusive to date." (PMID 34944977, 2021). "We found that SPP1, VIP, COL11A1, CA2, ADAM12, INHBA could provide great significant prognostic value for colon cancer." (PMID 30746900, 2019).
gastric cancer (7 papers, 2013 to 2025). A primary or metastatic malignant neoplasm involving the stomach. "Among different subtypes of gastric cancer, CA2 mRNA was significantly different in CIN and MSI (p = 0.003) and GS and MSI (p = 0.013)." (PMID 40995432, 2025). "Therapeutical agents and changes in the expression or activity of some Ca2+ channels and pumps in gastric cancer." (PMID 38370477, 2024). "Low CA2 expression is negatively correlated with cancer size, distant metastasis, pathological stage, and poorer overall survival in gastric cancer." (PMID 36631756, 2023). "It has been found that low CA2 expression in gastric cancer and non-small cell lung cancer promotes tumor proliferation and metastasis." (PMID 36778142, 2023). "A low CA2 expression negatively correlates with pathological state, distant metastasis, and tumor size in gastric cancer." (PMID 37895185, 2023). "The expression of CA2 remains controversial in different cancers, it was reported to be upregulated in urinary bladder cancers, and CA2 autoantibody titers in gastric cancer patients were found higher compared to healthy subjects, while in esophageal adenocarcinoma, its expression was downregulated." (PMID 32256214, 2020). "Analysis by the GEPIA database revealed (tumor = 408, normal = 211) that CA2 and HSP90AA1 were differentially expressed in gastric cancer, CA2 (p < 0.05) was lowly expressed in gastric cancer, and HSP90AA1 (p < 0.05) was highly expressed in gastric cancer." (PMID 40995432, 2025). "In this experiment, WGCNA and machine learning algorithms were used to predict CA2, HSP90AA1, and NR3C1, the core targets of white Atractylodes against gastric cancer." (PMID 40995432, 2025). "None of the promoter methylation expression levels of CA2, NR3C1, and HSP90AA1 were significantly different in gastric cancer." (PMID 40995432, 2025).
glioblastoma (7 papers, 2018 to 2022). The most malignant astrocytic tumor (WHO grade IV). "In any case, the link found between the Ca2+ channel auxiliary subunit and glioblastoma reveals this protein as a possible biomarker and/or therapeutic target." (PMID 36520928, 2022). "Recent studies reported consistently elevated expression levels of carbonic anhydrase CA2 in recurrent glioblastoma and temozolomide-resistant glioblastoma stem-like cells (GSCs)." (PMID 35008590, 2021). "qPCR conducted on mRNA extracted from freshly frozen tissue samples consistently displayed an up-regulation of CA2 in all glioblastomas at recurrence." (PMID 31262047, 2019). "Combined, this suggests that targeting of glioblastoma Ca2+ channels by benidipine or other FDA-approved Ca2+-antagonists such as nifedipine seems to be clinically feasible." (PMID 30669316, 2019). "Despite being known for its anti-Ca2+ channel activity, FLN has also been reported to induce autophagy-like activity in glioblastoma cells." (PMID 30446677, 2018).
lung carcinoma (7 papers, 2012 to 2022). "In lung cancer xenograft mouse models, shRNA-mediated knockdown of CA2 impaired tumor cell proliferation and angiogenesis and induced apoptosis." (PMID 34997121, 2022). "Using the specific blockers of Ca2+ channels, pumps and/or exchangers has demonstrated the significant antitumor effects on lung cancer progression, indicating that Ca2+ signaling would be a promising target for novel lung cancer treatments." (PMID 36046435, 2021). "In addition, altered expression of specific Ca2+ channels and Ca2+-binding proteins can contribute to tumorigenesis and tumor growth in lung cancer." (PMID 34745971, 2021). "Therefore, identification of the key Ca2+ channels, pumps and/or exchangers would be beneficial for development of treatment strategies for lung cancer." (PMID 36046435, 2021). "In addition, it is unknown whether bone resorption-derived (Ca2+)e might have been responsible for activating the Ca2+ channels, pumps and exchangers to promote differentiation and growth of metastatic lung cancer cells (MLCCs) in bone." (PMID 36046435, 2021).
rheumatoid arthritis (7 papers, 2002 to 2024). A chronic, systemic autoimmune disorder characterized by inflammation in the synovial membranes and articular surfaces. "Annexin A2, a Ca2+-regulated membrane binding protein with key roles in membrane-cytoskeleton and membrane-membrane binding events, has been shown to be an autoantigen in several immune-mediated diseases including anti-phospholipid syndrome and rheumatoid arthritis (RA)." (PMID 33043033, 2020).
cardiac hypertrophy (6 papers, 2013 to 2023). "miR-328 is a strong pro-fibrotic miRNA in the heart, governing atrial fibrillation through targeting the genes encoding Ca2+ channels and promoting cardiac hypertrophy that is considered the primary predictor of chronic heart diseases and cardiomyopathy." (PMID 36984840, 2023). "The role of Ca2+ channels in the pathogenesis of cardiac hypertrophy has been extensively investigated but no safe conclusions can be extracted." (PMID 36751183, 2023).
depression (6 papers, 2018 to 2025). "The results showed that in the depression group, Neutrophil Degranulation, Antimicrobial Peptides, Complement System, Formation of Fibrin Clot Clotting Cascade, Response To Elevated Platelet Cytosolic CA2, and other immune-related pathways were significantly enriched." (PMID 40595897, 2025). "In addition, the CA2 projections appear to have a key role in social memory, which is in line with the current observations that the CA2 projections may have a role in depression." (PMID 29865267, 2018).
prostate carcinoma (6 papers, 2017 to 2023). A carcinoma that arises from epithelial cells of the prostate gland. "In the context of malignancies, TRPM7 is a Ca2+ and Mg2+ permeable ion channel which is associated with the growth and progression in breast, gastric, pancreatic, and prostate cancers." (PMID 35771152, 2022). "Anoctomin-7 (ANO7) is a member of the anoctamin family of Ca2+ activated Cl− channels, highly expressed by the prostate, and associated with aggressive prostate cancer." (PMID 33114768, 2020). "Our recent findings indicated that the hallmark Ca2+ channel of the prostate epithelium TRPM8 undergoes targeted degradation in the prostate cancer cell line, LNCaP." (PMID 28039451, 2017). "For example, an increase in the expression of the Ca2+ channels TRPV2 in prostate cancer, and TRPM8 in squamous cell carcinoma resulted in induction of MMP-2 and MMP-9, respectively." (PMID 33802790, 2021). "In our study, we also found reduced CA2 expression in prostate cancer tissues, but whether this promotes tumor progression in prostate cancer remains unknown and needs to be investigated further." (PMID 36778142, 2023).
asthma (5 papers, 2013 to 2023). "To date, however, few studies have reported on the relationship between SLC40A1, SLC39A8, CA2, and asthma, or examined the functional roles of the five IMR genes in iron homeostasis imbalance." (PMID 37123407, 2023). "Currently, therapeutic measures for asthma treatment involving calcium include the blockers for chloride channels (e.g., sodium cromoglicate and nedocromil sodium) and the Ca2+-activated K+channel, KCa3.128–30." (PMID 37752127, 2023). "Given that airway inflammation and asthma have been linked to oxidative stress, we investigated whether TRPM2, a Ca2+-permeable ion channel involved in ROS signaling, contributes to pathophysiology." (PMID 23631390, 2013).
Cognitive impairment (5 papers, 2019 to 2023). Abnormal cognition is characterized by deficits in thinking, reasoning, or remembering. "However, the extent to which CA2 contributes to these cognitive deficits, such as social interaction and temporal ordering, remains uncertain." (PMID 37509636, 2023). "In addition, the loss of CA2 cholinergic fibres appeared to be a more sensitive marker as it distinguished PD cases with cognitive impairment from cases with no reported cognitive deficit." (PMID 31023342, 2019).
cyst (5 papers, 2021 to 2025). A sac-like closed membranous structure that may be empty or contain fluid or amorphous material. "PC1 is a mechanosensor that controls PC2, a Ca2+-permeable cation channel that, by regulating cytoplasmic Ca2+, prevents adenylyl cyclase producing cyst-promoting concentrations of cAMP." (PMID 39922884, 2025). "Inactivation of carbonic anhydrase 2 (Car2) significantly reduced, whereas, deletion of Foxi1 completely abrogated the cyst burden in Tsc1 KO mice." (PMID 38731991, 2024). "Recent data have consistently shown that the cyst growth in ADPKD mouse models was inhibited through different pharmacological inhibitors of the Ca2+-activated chloride channel." (PMID 35892566, 2022). "Such comparison resulted in 4 upregulated (CP, CEACAM5, DMBT1, and KRT6A) and 8 downregulated (CEL, CPA1, CPB1, ALB, SERPINA4, CA2, CLU, and AMBP) DEGs secreted in cyst fluid of high-risk IPMNs." (PMID 34790815, 2021).
myocardial infarction (5 papers, 2015 to 2024). Gross necrosis of the myocardium, as a result of interruption of the blood supply to the area, as in coronary thrombosis. "For example, CA2 is a critical target for the treatment of myocardial infarction." (PMID 39872885, 2024).
psoriasis (5 papers, 2021 to 2025). An autoimmune condition characterized by red, well-delineated plaques with silvery scales that are usually on the extensor surfaces and scalp. "AIF1, another potential target of psoriasis, is a Ca2+-binding EF-hand cytokine encoded in the major histocompatibility complex III region on chromosome 6." (PMID 39883516, 2024). "Moreover, NELL2 (neural epidermal growth factor-like 2) and CA2 (carbonic anhydrase 2) that are representative of atopic dermatitis and differentiates from psoriasis were also upregulated." (PMID 33806193, 2021).
adenoma (4 papers, 2018 to 2023). A neoplasm arising from the epithelium. "Low CA2 expression may promote adenoma cell stemness and serve as a biomarker for high-risk adenomas." (PMID 36631756, 2023). "Overall, in the study, we systematically explored the differences in molecular expression profiles of colorectal mucosa and adenomas, elucidating enriched pathways, hub genes (CA2 and HSD11B2), disease prognosis and immune patterns." (PMID 36631756, 2023). "The reduced expression of CA2 may enhance the stem-cell-like characteristics of adenoma cells in CRC and could potentially serve as a marker for high-risk CRC adenomas." (PMID 37895185, 2023). "The genes CA2, CA7, and ITM2C collectively play critical roles in CRC progression, with CA2 influencing adenoma characteristics and cell proliferation, CA7 acting as a tumor suppressor gene, and ITM2C likely sharing similar tumor-suppressive properties with its family member ITM2A." (PMID 37895185, 2023).
Anxiety (4 papers, 2021 to 2025). Intense feelings of nervousness, tension, or panic often arise in response to interpersonal stresses. "Our findings add to a growing body of work suggesting CA2 is important to consider as a potential target for therapeutic treatments for individuals with anxiety and MDD who have been exposed to early life stress." (PMID 41361727, 2025). "Future studies manipulating MRs in a more time-dependent manner (i.e., viral mediated knockout of MRs in adulthood) are needed to further clarify the apparent role of MRs in CA2 in regulating anxiety-like behavior." (PMID 31745235, 2021). "The role of MRs and/or CA2 in anxiety are likely to be complex and are possibly sex-dependent." (PMID 31745235, 2021). "The mice with CA2 neural inhibition displayed the classical social memory defect in three-chamber social test without the defects of social ability, anxiety level or motion ability." (PMID 37303064, 2023).
Arrhythmia (4 papers, 2023 to 2025). Any cardiac rhythm other than the normal sinus rhythm. "This can lead to mitochondrial dysfunction, which causes cell death and the acceleration of Ca2+-dependent proteases, including CaMKII and protein kinase A, which could contribute to the development of HF and arrhythmia in patients with DMD and mdx mice." (PMID 38028197, 2023). "Most of the evidence points to a pro-hypertrophy, proinflammatory and pro-fibrotic effect of p38 activation on the onset of HF and arrhythmias, which involves cardiac fibrosis, alterations to Ca2+-handling proteins, and the modulation of gap junctions in cardiomyocytes." (PMID 40610735, 2025). "Our results highlight the detrimental impact of ROS, such as hydroxyl radicals, superoxide, and hydrogen peroxide, on Ca2+-regulating proteins, with pronounced associations in multiple CVD categories, notably arrhythmias, cardiac conduction system diseases, and cardiomyopathy." (PMID 39594561, 2024).